INS (insulin)
Diseases named in the same sentence as INS in open-access papers (continued):
Sharing a sentence is not in itself a finding about the gene and the disease.
Hyperglycemia (continued). "We found that Men1 excision prevented STZ-induced hyperglycemia, at least partly through promoting beta-cell proliferation, and preserving the number of functional beta cells and circulating insulin levels." (PMID 21318185, 2010). "Twenty (42.6%) developed critical illness hyperglycemia, defined as persistent BG levels >140 mg/dL (7.7 mmol/L), and received insulin via our published pediatric-specific hyperglycemia protocol." (PMID 20925914, 2010). "The benefit of early elective insulin therapy in the prevention and treatment of hyperglycemia has been demonstrated in critically ill adults, but is questionable in premature infants." (PMID 20646308, 2010). "The study was planned to evaluate the insulin-sensitizing effects of the insulin plant (Costus igeus) in dexamethasone-induced hyperglycemia in male albino rats." (PMID 20814523, 2010). "This chronic hyperglycemia is suggested to lead to the dysfunction of beta cells in the pancreas thus decreasing insulin release." (PMID 22254008, 2010). "Insulin production is eventually insufficient for maintaining normal blood glucose levels in T1D or T2D, leading to hyperglycemia and secondary complications, including cardiovascular disease, kidney dysfunction, and blindness." (PMID 21318185, 2010). "Hyperglycemia of Akt1(+/−)Akt2(−/−) mice is significantly attenuated by restoring plasma leptin level concomitant with increased circulating insulin level." (PMID 21113299, 2010). "Animals in the untreated STZ diabetic group displayed severe hyperglycemia, significant decrease in the levels of insulin and an increase in the LVM/BW ratio (as an index of ventricular hypertrophy)." (PMID 21118576, 2010). "Another beneficial effect of PARP inhibitors like 3-AB, in addition to preventing pancreatic damage by a diabetogenic agent, is to preserve the ability of the pancreas to secrete insulin in response to hyperglycemia." (PMID 20804590, 2010). "We found a high correlation between BG and CGM readings (98.2% in Zone A + B) in patients who required an insulin infusion for critical illness hyperglycemia." (PMID 20925914, 2010). "Among the 26 subjects, two cases demonstrated hyperglycemia, although the hyperglycemia was corrected after hypodermal insulin administration and deceleration of GIK." (PMID 21187862, 2010). "Rabbits and dogs following scorpion envenomation present a reduction of insulin, hyperglycemia, and enlace glycogenolisis in heart, liver, and skeletal muscle." (PMID 20300540, 2010). "Gene expression analyses of liver RNA confirmed an elevated expression of insulin genes in the liver tissue exposed to hyperglycemia." (PMID 20195523, 2010). "• Discontinue insulin therapy immediately after the birth in women who were diagnosed with GD; test their blood glucose to exclude persisting hyperglycemia before transfer to community care, and remind them of the symptoms of hyperglycemia." (PMID 20416099, 2010). "The hyperglycaemia and ketoacidosis resolved by the 14th hour of treatment, consisting of IV insulin and rehydration." (PMID 21274328, 2010). "The presented data demonstrates that the inhibition of the NFκB pathway in vitro protects against beta cell failure and in vivo protects against hyperglycaemia and decreased pancreatic insulin content." (PMID 20948968, 2010). "In the diabetic state, hyperglycemia per se and subsequent production of ROS decrease insulin gene expression and secretion and finally bring about apoptosis." (PMID 20182627, 2010). "In this study all patients were administered an intensified insulin along with antihypertensive therapy so that the confounding effects of hyperglycemia and hypertension were minimized." (PMID 21108832, 2010). "Male SDT rats exhibit noticeable hyperglycemia, polyuria, and glucosuria concomitant with diminished blood insulin levels and decreased body weight by 15–20 weeks of age." (PMID 20508774, 2010).
Hyperglycemia (continued). "Treatment with insulin therefore not only corrects hyperglycaemia, but also directly affects the brain." (PMID 20868513, 2010). "We investigated the effects of neonatal hyperglycemia (blood glucose ≥ 10 mmol/l, treated with insulin for ≥ 12 hours) on growth and neurobehavioral outcome at 2 years of age." (PMID 20646308, 2010). "During the second year of life, as hyperglycemia severely worsens, insulin release decreases, islets display a marked disruption of the architecture and the percentage of β cells diminishes." (PMID 20236525, 2010). "Since twenty-five years continuous insulin infusion is used, nevertheless in many centers restriction of glucose intake is still the first step in treatment of hyperglycemia." (PMID 20646308, 2010). "For type 1 and late stage type 2 diabetic patients, a common method of alleviating hyperglycemia is by subcutaneous administration of exogenous insulin before each meal." (PMID 19642985, 2009). "The conclusion is that the type 1 diabetic patients that presented lower BMI and lower insulin dose in the pretransplant period were the ones that developed hyperglycemia less frequently, i.e., approximately in 11%." (PMID 19825194, 2009). "Traditional diabetic agents such as insulin and sulfonylureas predominantly lower fasting glucose and are less effective at reducing postprandial hyperglycemia." (PMID 19402896, 2009). "In contrast, mice treated with streptozotocin alone developed hyperglycemia and circulating insulin levels that were significantly decreased." (PMID 20148083, 2009). "Persistent hyperglycaemia of any aetiology represents a state of metabolic dysregulation resulting from an imbalance of insulin production and insulin sensitivity in target tissues." (PMID 19245691, 2009). "Due to the inconvenience of insulin administration, it has long been a primary goal of many pharmaceutical companies to develop an orally active therapeutic agent for treating hyperglycemia in diabetic patients." (PMID 19642985, 2009). "We examined the use of a computerized insulin dosing algorithm to manage hyperglycemia with particular attention to frequency and conditions surrounding hypoglycemic events." (PMID 19822000, 2009). "We routinely screen for and treat hyperglycaemia with insulin in our PICU, and have reported that about 20% of all our admissions develop CIH." (PMID 19245691, 2009). "As a consequence of increased hyperglycaemia, plasma insulin levels increased to adapt glucose uptake by the different tissues." (PMID 19956534, 2009). "This is a retrospective analysis of adult patients with hyperglycemia receiving intravenous (IV) insulin therapy from March 2006 to December 2007 in the intensive care units of 2 tertiary care teaching hospitals." (PMID 19822000, 2009). "The major function of insulin is to counter the concerted action(s) of a number of hyperglycemia-generating hormones and to maintain low blood glucose levels." (PMID 20379410, 2009). "In the present study, insulin content was severely reduced after extended hyperglycemia similar to what was previously observed in INS-1E cells and primary islets." (PMID 19607692, 2009). "The rat spontaneously develops hyperglycemia and glucose intolerance resulting from decreased insulin secretion due to β-cell degeneration." (PMID 19696902, 2009). "Although these studies indicate that insulin has the potential to improve hyperglycemia induced alteration of HSPG in ECs, the effect is time dependent." (PMID 19695080, 2009). "For instance, we show that when normoglycemia is restored by exogenous insulin or islet transplantation, the β-cell proliferation rate returns towards low levels found in control animals, yet surges when hyperglycemia recurs." (PMID 19287497, 2009). "The metabolic features of STZ-diabetic rats include the prompt development of profound hyperglycemia (607 ± 16 mg/dl)) and markedly reduced plasma insulin levels (1.08 ± 0.16 μg/L)." (PMID 19706162, 2009).
Hyperglycemia (continued). "Within this context, it becomes important to mention the low capacity of regeneration/neogenesis of beta cells mainly when they are exposed to hyperglycemia, which is a stimulus metabolic factor to the insulin secretion, but it is also glycotoxic." (PMID 19961609, 2009). "Glycemic and insulin level analyses showed that during fasting, 23.5% of the glucose values were high, characterizing hyperglycemia." (PMID 19893939, 2009). "Diabetics and older (> 35 years of age) patients require insulin supplementation for optimum metabolic balance to avoid hyperglycemia during the initial 24 hours postoperatively." (PMID 19374754, 2009). "Since the hormone insulin regulates glucose metabolism and promotes glucose uptake and utilization to reduce glucose concentration in hyperglycemia, we also wished to determine the effect of insulin on GAG alterations." (PMID 19695080, 2009). "Here we show that early deficits in insulin and C-peptide availability and decreased presence of IGF-1 as well as hyperglycemia are associated with impaired functions of unmyelinated and myelinated nerve fibers." (PMID 19834568, 2009). "Observational studies outside of clinical trials supported these results, finding improved outcomes after intensive insulin therapy to manage hyperglycemia in the critically ill patient." (PMID 19822000, 2009). "As it has been observed that broilers are insulin and hyperglycemia resistant, we proposed that GCLC would be a potential regulator in hyperglycemia resistance process for broiler chickens." (PMID 19232135, 2009). "Early preceding functional deficits are believed to be metabolically induced by decreased Na+/K+-ATPase and eNOS activities precipitated by impaired insulin action and hyperglycemia." (PMID 19834568, 2009). "Hyperglycemia is managed by augmenting insulin secretion and/or interaction with hepatic glucose production, as well as by decreasing dietary caloric intake and raising glucose metabolism through exercise." (PMID 19794883, 2009). "The progressive impairment of beta cell function and increased insulin demand as tissue becomes insulin resistant are core pathophysiologic defects in the development of hyperglycemia in T2DM." (PMID 19619327, 2009). "It is characterized by central obesity, hypertension, hyperglycemia and reduced response to insulin (insulin resistance)." (PMID 19822001, 2009). "For patients still requiring insulin to control hyperglycemia at time of hospital discharge, we recommend discharge with an appropriate individualized antihyperglycemic medicine." (PMID 19025628, 2008). "Impaired insulin stimulated glucose uptake and utilization in adipocytes of congenic rats contributes to hypertriglyceridemia and hyperglycaemia, which in turn stimulates insulin secretion." (PMID 18698428, 2008). "We studied effect of cutch, a product of Acacia catechu on hydrocortisone and glucose induced hyperglycemia to assess its effects on gluconeogenesis and insulin secretion." (PMID 21593974, 2008). "This implies that this patient tends to try to avoid hyperglycemia by injecting a greater dose of insulin than what is recommended by the guideline." (PMID 19061492, 2008). "All but one patient received intravenous insulin (20–260 IE per day of Actrapid, Novo Nordisk) to control hyperglycemia." (PMID 18997871, 2008). "Chronic hyperglycemia also activates transcription of the insulin gene, resulting in de novo synthesis of insulin." (PMID 19007436, 2008). "In the pathopysiology of T2DM, impaired insulin sensitivity and glucose intolerance are early phenomena, leading to hyperglycemia, hyperlipidemia and, eventually, to a failure of pancreatic beta cells to produce and secrete a sufficient amount of insulin." (PMID 18590522, 2008). "This relative hyperglycaemia increases pancreatic insulin production, as shown by the increase in C-peptide (secreted at equimolar concentrations with insulin) in both patient subgroups." (PMID 18665244, 2008).
Hyperglycemia (continued). "Meal-time doses of a short-acting insulin are indicated if postprandial hyperglycaemia is believed to be a particular problem." (PMID 19143853, 2008). "In this regard, a biphasic insulin analogue needs only twice-daily injections, and is able to correct postprandial hyperglycemia." (PMID 18507868, 2008). "In this group, WT→Jnk1−/− mice developed relative hyperglycemia and had increased fasting plasma insulin levels compared to Jnk1−/−→Jnk1−/−." (PMID 18773087, 2008). "The high incidence of hyperglycaemia identified in this study confirms the need to study the effect of insulin in detail." (PMID 18218076, 2008). "Hyperglycemia as well as insulin and insulin precursor molecules stimulate the transcription of PAI-1." (PMID 18615155, 2008). "Someof these studies hadalso administered systemic ocreotide to suppress insulin secretion response to hyperglycemia." (PMID 18350125, 2008). "The phenotypes of B6.DBA congenic mice include reduced β-cell replication rates accompanied by reduced β-cell mass, reduced insulin/glucose ratio in blood, reduced glucose tolerance, and persistent mild hypoinsulinemic hyperglycemia." (PMID 18654634, 2008). "The average nutrition intake is lower and the average insulin rate is higher during the initial phase of controlling hyperglycaemia." (PMID 18412978, 2008). "As initial therapy with a basal insulin reduces HbA1C towards target, this gain is likely to owe more to improved fasting glucose levels than a reduction of postprandial hyperglycaemia." (PMID 19143853, 2008). "Uncoupling proteins therefore have become an interesting focus for hyperglycemia mediated impaired insulin secretion." (PMID 18167556, 2008). "The addition of insulin to maintain normoglycemia resulted in reduced inflammation 3 days after the injury compared with rabbits under hyperglycemia." (PMID 18710523, 2008). "A once-daily long-acting basal insulin controls basal hyperglycaemia more effectively than meal-time injections of short-acting insulin; conversely, it controls postprandial glucose levels less effectively." (PMID 19143853, 2008). "During a prolonged stay in the Intensive Care Unit (ICU), total parenteral nutrition (TPN, 0.83 mol/l glucose, 104 ml/h) was started and an ICU insulin infusion protocol was utilized to manage hyperglycaemia." (PMID 18644072, 2008). "The Cochrane review also found that acarbose is at least as effective at controlling postprandial hyperglycaemia as commonly used oral antidiabetics, short-acting insulin secretagogues and the long-acting sulphonylurea glibenclamid." (PMID 17697384, 2007). "Thus insulin replacement in the newborn could reverse the risk associated with high blood sugar: it could improve anabolism and weight gain, and theoretically by reducing hyperglycaemia, reduce risk of sepsis." (PMID 17692117, 2007). "We designed this system so that patients who receive steroids both get higher initial insulin doses, and are checked more frequently to promptly detect hyperglycemia." (PMID 18086312, 2007). "We introduced four evidence-based clinical protocols (lung protective strategy for ALI, activated protein C for septic shock, intravenous insulin for hyperglycemia control, and sedation/analgesia protocol) in the MICU between February 2002 and April 2004." (PMID 17686165, 2007). "Whilst oral glucose tolerance tests and eugylcaemic clamp studies are the gold standard for determining hyperglycaemia and insulin resistance they are difficult to conduct in large scale epidemiological studies." (PMID 17760500, 2007). "Current neonatal practice of intermittent insulin treatment is only partially effective at controlling hyperglycaemia in the infants who require intensive care." (PMID 17692117, 2007). "One study in premature infants using continuous insulin infusions to control hyperglycaemia showed better glucose tolerance with improved weight gain combined with a reduced incidence of sepsis." (PMID 17692117, 2007).
Hyperglycemia (continued). "As the benefits of insulin therapy are related to the level of achieved glucose control, the impact of corticosteroids on hyperglycemia has become more relevant." (PMID 18086312, 2007). "Neonatal diabetes mellitus (NDM) is a rare (1:300,000–400,000 newborns) but potentially devastating metabolic disorder characterized by hyperglycemia combined with low levels of insulin." (PMID 17349054, 2007). "Insulin production is inadequate with a low blood level in comparison with the hyperglycemia, and therefore exogenous insulin therapy is required." (PMID 17349054, 2007). "Treatment of hyperglycemia by continuous insulin infusion has recently been shown to improve outcome." (PMID 18086312, 2007). "Despite some uncertainties, the management of hyperglycemia utilizing insulin protocols is fast becoming a new standard in critical care practice." (PMID 17727725, 2007). "α-lipoic acid supplementation is known to provide a beneficial effect in diabetic patients via mechanisms including attenuation of hyperglycemia, suppression of advanced glycation end production formation and improved insulin sensitivity." (PMID 23675004, 2006). "This phenomenon can be interpreted as an adaptation response of beta cells to the hyperglycemia documented between d6 and d20 and to the elevated basal insulin secretion observed at d20 when compared to d28." (PMID 17183663, 2006). "HL was almost invariably accompanied by hyperglycemia due mainly to increased glucose production, which was probably due to the release of stress hormones and cytokines leading to insulin resistance." (PMID 17134504, 2006). "Impaired early insulin secretory response of the pancreatic β-cell and decreased insulin sensitivity of muscle, fat and liver cells contribute to the state of hyperglycemia." (PMID 17163994, 2006). "Insulin and insulin-sensitizer combinations significantly improve hyperglycemia; however, there is an increased incidence of heart failure reported with this combination, prompting close monitoring of patients for signs and symptoms of heart failure." (PMID 15736996, 2005). "First of all, this approach is based on a retrospective treatment for hyperglycemia, which reflects the degree of insulin sensitivity and glucose disposal rate in the preoperative period." (PMID 15916471, 2005). "Peripheral tissues become insulin resistant and lose nutrients into the blood, sometimes producing hyperglycemia and eventually the familiar cachexia of the cancer patient." (PMID 16111485, 2005). "Van den Berghe and coworkers found that lowering postoperative hyperglycaemia with intensive insulin therapy significantly decreased morbidity and mortality in postoperative patients." (PMID 15566589, 2004). "Endogenous insulin secretion remained intact, and hyperglycemia improved after admission." (PMID 41536580, 2026). "Insulin treatment normalized hyperglycemia, reduced albuminuria, and decreased glomerular fibrosis." (PMID 41601953, 2026). "It is known that maternal obesity and GDM are closely intertwined, both being characterized by metabolic derangements such as hyperglycemia, inflammation, hyperinsulinemia, hyperleptinemia, and dyslipidemia in the mothers, and that their fetuses tend to exhibit higher insulin levels." (PMID 40920364, 2026). "In a similar way, a high protein evening meal may help protect individuals with T1D from overnight hypoglycemia, but excessive consumption of protein might contribute to nocturnal hyperglycemia unless the prandial insulin dose is titrated accordingly." (PMID 41602572, 2026). "TCA cycle function and oxidative phosphorylation are also essential for insulin release and cellular response to insulin; therefore, their impairment could explain the persistent hyperglycemia observed in our cases." (PMID 41458137, 2026).